VCAM1 (vascular cell adhesion molecule 1)
Diseases named in the same sentence as VCAM1 in open-access papers (continued):
Sharing a sentence is not in itself a finding about the gene and the disease.
co-infection (8 papers, 2011 to 2025). "The elevation of VCAM-1 concentrations in HCV coinfection is common and seems to decrease with HCV eradication." (PMID 40006998, 2025). "In our analysis, people with HIV/HCV coinfection who died had significantly higher concentrations of VCAM-1 than those who lived." (PMID 40006998, 2025). "In our study, expression of both CCL2 and VCAM-1 genes was significantly increased after co-infection of swine epithelial cells." (PMID 24708855, 2014). "Moreover, there was a significant correlation between VCAM-1 levels and AST levels, which suggests that necroinflammatory activity in the liver and endothelial activation are linked phenomena in the setting of HIV/HCV coinfection." (PMID 32575428, 2020). "We observed significant differences in mean values of the duration of HIV infection, the presence of HCV coinfection, and serum concentrations of CRP, PCT, total cholesterol, triglycerides, and VCAM-1 among patients who lived and patients who died." (PMID 40006998, 2025). "The baseline lipid profile, CD4+ cell count, platelets, CRP, PCT, TNF-α, VCAM-1, and HCV and HBV coinfection were evaluated." (PMID 40006998, 2025). "The TAK-242/siRNA-treated IAV+SA group exhibited markedly decreased mRNA levels of inflammatory factors (NF-κB, IL-6, TNF-α) and adhesion molecules (ICAM-1, VCAM-1) compared with the uninfected IAV+SA group, confirming TLR4 as the key receptor mediating co-infection-induced inflammation." (PMID 40572089, 2025). "We also did not observe a significantly higher concentration of VCAM-1 among patients with HBV co-infection." (PMID 35336985, 2022).
endotoxemia (8 papers, 2009 to 2025). "We investigated acute endotoxemia-induced changes in the expression of Tie2 and inflammation-associated endothelial adhesion molecules E-selectin and VCAM-1 (vascular cell adhesion molecule-1) in kidneys and lungs in inducible, EC-specific Tie2 knockout mice." (PMID 37508516, 2023). "Summarizing, low to absent Tie2 expression in vivo in renal arterioles was associated with higher basal VCAM-1 protein expression, and in lung capillaries with higher endotoxemia-induced E-selectin protein expression." (PMID 37508516, 2023). "Adhesive factors such as intercellular adhesion molecule 1 (ICAM1) and vascular cell adhesion molecule 1 (VCAM1) are scarcely expressed in the intact endothelium but are up-regulated by endotoxemia and facilitate the recruitment of inflammatory cells." (PMID 38550779, 2024). "To achieve this, we challenged Tie2∆E9 knockout and control mice with LPS and studied the effects of this acute inflammatory stimulus on Tie2 expression and on the extent and location of E-selectin and VCAM-1 expression 4 h after the start of endotoxemia." (PMID 37508516, 2023). "This study reveals that, although local accumulation of the targeted drug was achieved, endothelial targeted dexamethasone containing anti-VCAM-1 SAINT-O-Somes exhibited marginal effects on inflammatory endothelial cell activation in a model of endotoxemia." (PMID 29763440, 2018). "In summary, we here reported the accumulation of dexamethasone loaded anti-VCAM-1 SAINT-O-Somes in endotoxemia activated VCAM-1 expressed microvasculature." (PMID 29763440, 2018). "In a murine endotoxemia model, VCAM-1 was shown to be involved in endotoxin-induced leukocyte sequestration." (PMID 29601599, 2018). "In the current study, we aimed to evaluate the targeting specificity of dexamethasone loaded anti-VCAM-1 (AbVCAM-1) SAINT-O-Somes to inflamed endothelium in an endotoxemia mouse model as well as their effects on microvascular endothelial activation in vivo." (PMID 29763440, 2018). "RAGE induces VCAM-1, used by PMNs to adhere to and infiltrate the myocardium during endotoxemia with subsequent oxidative and nitrosative stress leading to myocardial dysfunction in an experimental study." (PMID 19508707, 2009). "The 4 h time point was chosen as previous experiments showed that E-selectin and VCAM-1 expression induction occurred within the first 4–8 h after LPS exposure in this murine endotoxemia model, and did not further increase in time." (PMID 37508516, 2023).
Hepatitis (8 papers, 2008 to 2024). Inflammation of the liver. "Expression of VCAM-1 is significantly enhanced in mice that develop hepatitis after ConA injection, while the role of PECAM-1 in leukocyte transmigration during the liver inflammation is well known." (PMID 33809904, 2021). "The pro-inflammatory markers IL-1α, IL-1β, IL-6, TNF, ICAM-1, and VCAM-1 were all significantly upregulated under both hepatitis models." (PMID 29445190, 2018). "Lipotoxic stress enhances the expression of VCAM-1 in LSECs through MLK3/P38 signaling, while inhibition of VCAM-1 can inhibit adhesion and transendothelial migration of monocytes across LSECs (from wild-type mice fed a high-fat diet and from ob/ob obese mice) and improves liver inflammation." (PMID 38943171, 2024). "Our study demonstrated that APAP and ROX co-treatment significantly increased the expression levels of TNF-α, INF-γ, VCAM-1, CXCL-1, STAT-3, Nrf-2, GSTA, GCLC-1, HO-1 and NQO1, suggesting that APAP and ROX co-treatment can induce liver inflammation." (PMID 32132876, 2020). "VCAM-1 and CXCL16 increased expression led to the recruitment of CXCR6+ cells by the liver, perpetuating the bystander hepatitis." (PMID 23110209, 2012). "The bystander hepatitis induced by TLR3 and TLR9 stimulation produced a steady increase in the expression of VCAM-1." (PMID 23110209, 2012). "We identified 7 proteins that significantly differentiate HCC patients from hepatitis patients (p < 0.05) (AFP, CTNNB, CSF1, SELL, IGFBP6, IL6R, and VCAM1)." (PMID 19578489, 2008).
acute lymphoblastic leukemia (7 papers, 2018 to 2025). Leukemia with an acute onset, characterized by the presence of lymphoblasts in the bone marrow and the peripheral blood. "Notably, the mechanism is different from those reported in the literature, i.e., VLA-4 (leukocytes or lymphoblastic leukemia cells)-VCAM1 (endothelial cells)." (PMID 35256780, 2022). "Also, CCL2, ICAM1 and VCAM1 have a positive effect on MSCs adhesiveness, survival and proliferation in patients with acute lymphoblastic leukaemia." (PMID 29495420, 2018). "Data from in vivo homing experiments also support a primary role of the VCAM-1-VLA-4 rather than the fibronectin-VLA-5 axis in the pathophysiology of precursor-B acute lymphoblastic leukemia (ALL) cells." (PMID 32210016, 2020).
allergic rhinitis (7 papers, 2018 to 2024). Inflammation of the nasal mucous membranes caused by an IgE-mediated response to external allergens. "Soluble intercellular adhesion molecule-1 (ICAM-1) and soluble vascular adhesion molecule-1 (VCAM-1) play important roles in allergic rhinitis (AR)." (PMID 35011854, 2021). "The aim of the study was the analysis of adhesion molecules' profile (ICAM-1, VCAM-1, and E-selectin) in patients with allergic rhinitis and the influence of H1 antihistamines on those markers." (PMID 30008985, 2018). "Furthermore, the MCODE plugin was employed to pinpoint 14 genes (Cyba, Nfkbia, Fos, Mpo, Il6, Il1b, Sele, Vcam1, F2, Tlr4, Alb, Egr1, Smad3, and Ptgs2) forming a primary cluster, potentially representing a crucial regulatory network for berberine in treating allergic rhinitis." (PMID 38796469, 2024). "Furthermore, eosinophil migration, which is dependent on the expression of cytokines, chemokines, and adhesion molecules (vascular cell adhesion molecule-1 (VCAM-1)), plays a key role in allergic rhinitis, as well as in IgE-mediated allergy." (PMID 30781605, 2019). "On the other hand, some researchers did not observe an increased level of ICAM-1 and VCAM-1 in serum of patients with allergic rhinitis." (PMID 30008985, 2018).
breast tumor (7 papers, 2015 to 2025). "For example, breast tumour cells overexpress vascular cell-adhesion molecule 1 (VCAM-1), a member of the transmembrane immunoglobulin superfamily." (PMID 36307871, 2022). "The excess VCAM-1 increased the recruitment of osteoclast precursors via directly interacting with the cognate receptor integrin α4β1, thus stimulating their adhesion to dormant breast tumour cells." (PMID 36307871, 2022).
essential hypertension (7 papers, 2015 to 2025). Hypertension that presents without an identifiable cause. "Increased levels of soluble VCAM1 have been observed in patients with primary hypertension and VCAM1 levels have been shown to be reduced after antihypertensive therapy." (PMID 33971895, 2021).
Hyperinsulinemia (7 papers, 2011 to 2024). An increased concentration of insulin in the blood. "Additionally, hyperinsulinemia augments TNFα-stimulated VCAM-1 expression above that seen for TNFα alone." (PMID 22093181, 2011). "We report that hyperinsulinemia augmented TNFα stimulated increases in VCAM-1 protein greater than seen with TNFα alone and decreased the time in which VCAM-1 translocated to the cell surface." (PMID 22093181, 2011). "Hyperinsulinemia and a perturbed PI3K pathway appear to augment TNFα stimulation of VCAM-1 protein, VCAM-1 translocation to the cell surface and nuclear import of NFκB." (PMID 22093181, 2011). "This study was performed in order to determine whether or not hyperinsulinemia increases the effects of TNFα-stimulated expression of VCAM-1 above that seen for TNFα alone and which molecular pathways in particular mediate this effect." (PMID 22093181, 2011). "An in vivo study showed that insulin concentration (10−9–10−7 mol/L) induced VCAM-1 expression and markedly increased TNF-α via NF-kB activation and IkB-α accumulation, so we suspect that hyperinsulinemia stimulates the expression of VCAM-1, not the blood pressure." (PMID 37822716, 2023).
liver diseases (7 papers, 2007 to 2022). "It shows that HCV RNA sequences seem to play a local effect on the endothelium, which can be the reason for increased levels of VCAM-1 in patients with liver diseases such as liver cirrhosis or chronic hepatitis C (CHC)." (PMID 35336985, 2022). "Hepatic VCAM-1 was only weakly expressed on human portal ECs but like ICAM-1, VCAM-1 expression was induced or upregulated by inflammatory cytokines and therefore detected at higher levels on vascular and sinusoidal ECs in inflammatory liver diseases." (PMID 31771248, 2019). "Further, circulating ICAM-1 and VCAM-1 do not exclusively result from liver diseases but are detected in other malignancies as well." (PMID 31771248, 2019). "Clinical studies showed that E-selectin and VCAM-1, (which were absent in normal human liver tissue), became strongly expressed in inflammatory liver disease." (PMID 17868448, 2007). "On this basis, VCAM-1 overexpression would not be a prime mechanism propagating portal hypertension but rather a secondary event that may be related to chronic vascular stress, inflammation, and phagocyte migration leading to nuclear factor kappaB (NF-kB) activation." (PMID 20961440, 2010).
myocarditis (7 papers, 2012 to 2025). Myocarditis is a condition that is characterized by inflammation of the heart muscle (myocardium). "Expression of ICAM-1 and VCAM-1 adhesion molecules on the cardiac (micro)vascular endothelium is upregulated upon infection with myocarditis-associated viruses." (PMID 35805941, 2022). "Since VCAM-1 is discussed as biomarker for the prediction of cardiovascular disease, routine determination of VCAM-1 levels in EMBs could be used for risk-stratification in myocarditis patients." (PMID 37568452, 2023).
acute respiratory distress syndrome (6 papers, 2016 to 2024). Progressive and life-threatening pulmonary distress in the absence of an underlying pulmonary condition, usually following major trauma or surgery. "In acute respiratory distress syndrome, accompanying lung damage, platelets promote the recruitment of immune cells by expressing intracellular adhesion molecule-1, vascular cell adhesion molecule-1, and P-selectin." (PMID 39287275, 2024). "A suppression of NF-ĸB-dependent gene expression, including IL-1β, TNF-α, and VCAM-1, was also observed with olaparib in a mouse model of acute respiratory distress syndrome." (PMID 35740913, 2022).
Allergy (6 papers, 2008 to 2023). An allergy is an immune response or reaction to substances that are usually not harmful. "For instance, IL-4, an important cytokine in allergic reactions, induces VCAM-1 in microvascular endothelial cells." (PMID 33321726, 2020). "In inflammatory conditions such as allergic diseases, MCps migrate across vascular ECs into the inflamed tissue via the interaction of α4β1 and α4β7 integrins on MCps with VCAM1 on ECs." (PMID 26659448, 2015).
brain infarction (6 papers, 2019 to 2024). Tissue necrosis in any area of the brain, including the cerebral hemispheres, the cerebellum, and the brain stem. "Alternatively, circulating immune cells can be activated, with blood–brain barrier damage after cerebral infarction, promoting the expression of cell adhesion molecules (ICAM-1, VCAM-1) in vascular endothelial cells." (PMID 37111353, 2023).
cardiomyopathy (6 papers, 2016 to 2025). A disease of the heart muscle or myocardium proper. "Based on our multi-omics analysis, we identified and validated CAT and VCAM1 as novel targets for treating DMD cardiomyopathy." (PMID 33869226, 2021). "However, as the disease progressed to the symptomatic stages of cardiomyopathy, VCAM-1 levels approached the concentrations observed in the indeterminate group." (PMID 40623042, 2025). "CLP-induced cardiomyopathy, indicated by reduced dP/dt and increased cardiac troponin I phosphorylation, was attenuated by BRL44408, this was associated with reduced cardiac TNF-α and endothelial VCAM-1 expression, cardiomyocyte apoptosis and related signal molecule phosphorylation." (PMID 29615637, 2018). "Together, our results provide a new insight in treating DMD cardiomyopathy via targeting of CAT and VCAM1, and serves as an example of translating Bed to Bench back to Bed using a muti-omics approach." (PMID 33869226, 2021). "Reduction of VCAM-1 and intercellular adhesion molecule 1 (ICAM-1) by CBD treatment has also been reported in an animal model of diabetes-induced cardiomyopathy, high glucose-induced endothelial cell barrier disruption, and in TNF-α exposed sinusoidal epithelial cell assays." (PMID 36109476, 2023).
chronic heart failure (6 papers, 2012 to 2025). "Vascular cell adhesion molecule 1 (VCAM-1), a transmembrane molecule acting as a mediator of immune cell adhesion to the vascular endothelium during inflammatory processes, has been shown to be associated in chronic heart failure and rheumatic disease." (PMID 30535754, 2019). "The ELISA results confirm that LA and ALA not only improve cardiac function in chronic heart failure but also exert vascular protective effects by reducing inflammatory cytokines, inhibiting NO overproduction, and decreasing serum levels of VEGF and VCAM-1." (PMID 41154077, 2025). "Up-regulation of VCAM-1 and TNF-α has been shown in the cardiac vascular endothelium from the patients with chronic heart failure." (PMID 26173590, 2015). "Up-regulation of VCAM-1 and TNF-α has been shown in the cardiac vascular endothelium from patients with chronic heart failure." (PMID 26173590, 2015). "In patients suffering from CAD and congestive heart failure, daily ingestion of flavanol-rich chocolate or cocoa for 28–42 days did not change CRP, P-selectin, E-selectin, ICAM-1, or VCAM-1." (PMID 27240397, 2016).
coronary atherosclerosis (6 papers, 2013 to 2025). Atherosclerosis of the coronary vasculature. "Future studies are needed to determine if these findings translate to human CAD patients, but this study strongly supports the development of VCAM-1 targeted agents as non-invasive diagnostic tools to longitudinally monitor the progression of peripheral and coronary atherosclerosis." (PMID 26702331, 2015). "Of major importance, the current study provides the first direct evidence that carotid VCAM-1 expression is predictive of coronary atherosclerosis in a large animal model." (PMID 26702331, 2015). "Most importantly, the preclinical studies from diabetic individuals with coronary artery atherosclerosis also indicate that immunoreactivity of SREBP-1 is predominantly localized in VCAM-1-positive vascular cells and lipid-rich macrophages of the plaques." (PMID 23825667, 2013). "Future studies to probe mechanisms will include blockade of VCAM-1, TNFα or IL-6 or depletion of neutrophils to examine the extent to which increased VCAM1, TNFα, IL-6 and neutrophilia with advanced age drives the increased burden of coronary artery atherosclerosis." (PMID 40403091, 2025).
glaucoma (6 papers, 2017 to 2025). Increased pressure in the eyeball due to obstruction of the outflow of aqueous humor. "Collectively, these findings support the notion that Th1 cells contribute to RGC loss in glaucoma by promoting VCAM-1 expression in retinal microvessels, thus facilitating the transmigration of Th1 cells into the neural retina." (PMID 38317227, 2024). "Cross-referencing with human genome-wide association studies data revealed overlap with glaucoma-associated genes (LTBP2, LOXL1, COL11A1, VCAM1), alongside reduced expression of Angpt and Lmx1b, linked to ocular hypertension." (PMID 41443436, 2025). "Given the similarities between the retina and CNS in terms of their neural tissue nature and shared developmental and pathological mechanisms, we investigated the involvement of VCAM-1 in our glaucoma model." (PMID 38317227, 2024). "Our study provides novel evidences showing the invasion of circulating Th1 cells into the retina through VCAM-1-mediated transendothelial migration in glaucoma, subsequently leading to retinal neurodegeneration." (PMID 38317227, 2024). "In the current study, animal experiments demonstrated the critical role of the interaction between β1+ Th1 cells and VCAM-1+ endothelial cells in glaucoma pathogenesis, and therapeutic strategies targeting this interaction were effective." (PMID 38317227, 2024). "Consistent with mass spectrometry findings, we observed that A2M, B2M, Clusterin, TNC, FVII, Adiponectin, CRP, SAA, ICAM-1 and VCAM-1 were differentially affected in the retinas and vitreous of glaucoma subjects." (PMID 28978942, 2017). "Collectively, these results shed light on the role of endothelial VCAM-1 in glaucoma pathogenesis and suggest that enhancing retinal microvessel expression of VCAM-1 might be one mechanism by which circulating Th1 cells breach the BRB and invade the retina." (PMID 38317227, 2024). "Therefore, our study aimed to investigate the involvement of VCAM-1 in glaucoma pathogenesis." (PMID 38317227, 2024). "Despite these findings, the role of VCAM-1 in glaucoma remains unknown." (PMID 38317227, 2024). "Moreover, our data showed that intravitreal injection of anti-VCAM-1 antibody effectively blocked the influx of circulating Th1 cells and alleviated retinal neurodegeneration, making it an attractive candidate for therapeutic intervention in glaucoma." (PMID 38317227, 2024). "The expression of cZBTB44, VEGFA and VCAM1 was significantly up-regulated in the AH of nAMD patients, while there was no increase in the AH of patients with age-related cataract (ARC) and glaucoma." (PMID 32194869, 2020).